IL10 (interleukin 10)
Diseases named in the same sentence as IL10 in open-access papers (continued):
Sharing a sentence is not in itself a finding about the gene and the disease.
COVID-19 (continued). "A unique feature of the COVID-19 induced cytokine storm compared to other SARS-CoV viruses, is a drastic elevation in IL-10 in critically ill patients." (PMID 35464430, 2022). "Another study also reported similar increase of Th17/Treg ratio in COVID-19 patients’ PBMC, which was related to poorer prognosis and lower abundance of Treg-relevant cytokines like IL-10 and TGF-β." (PMID 35874688, 2022). "The concentrations of granulocyte colony-stimulating factor (G-CSF), IL-2, IL-7, IL-10, TNF, and the chemokines, CCL2, CCL3, and CXCL10 were extremely high in the plasma of patients with severe COVID-19." (PMID 36294868, 2022). "According to a prospective study, the gut microbial composition was correlated with the increase of inflammation markers, including interleukin (IL)-10, tumor necrosis factor-α, and C-reactive protein (CRP) in COVID-19 patients." (PMID 35045853, 2022). "In COVID-19, authors demonstrated an increase in mRNA of ACE2, SARS-CoV2 receptor, in pulmonary cells, and in ECs in vitro after treatment with IL-10." (PMID 35631030, 2022). "An increased concentration of IL-6, TNF-α, IL-2, IL-8, IL-1β, G-CSF, IL-17, GM-CSF, IL10, MCP1, MIP1α, chemokines, galectins in serum, was detected in COVID-19 patients." (PMID 35075140, 2022). "The tear film concentrations of VEGF and IL-10 were found to be significantly increased, whereas TNF-α, IL-1β, IL-8, and GM-CSF were significantly lower among the COVID-19 patients admitted to the hospital than among the SARS-CoV-2-negative controls." (PMID 35566776, 2022). "Severe cases of COVID-19 develop cytokine storms characterized by excessive systemic release of multiple cytokines including IP-10 (CXCL10), IL-6, IL-8 (CXCL8), and IL-10." (PMID 35247068, 2022). "In conclusion, the major cytokines in COVID-19 pathophysiology, including IL-6, IL-8, and TNF-α, are significantly improved by Photobiomodulation, as is the IL-6/IL-10 ratio." (PMID 35874678, 2022). "Many investigations have reported high levels of pro-inflammatory cytokines and chemokines, including IL-2, IL-6, IL-10, IFN-γ, CXCL10, and CCL2 in COVID-19." (PMID 35664675, 2022). "Specifically, ncfDNA was correlated with cytokines/chemokines such as IL-15, IL-8, Eotaxin-3, IL-1β, IL-10, IL-16, VEGF, IL-6, IL-7, GM-CSF and IL-1α in SOTRs with COVID-19." (PMID 35075453, 2022). "We first observed a significantly elevated level of 7 serum cytokines (IL-1Ra, IL-2, IL-3, IL-10, IL-12p40, CXCL10, and HGF) in all COVID-19 cases when compared with controls." (PMID 35386707, 2022). "Future studies expanded these findings, demonstrating sustained increases in serum IL-2, IL-6, IL-10, and IFN-γ in severe COVID-19 cases, with higher IL-6 levels correlating with mortality risk." (PMID 35401519, 2022). "In this study, we identified that the serum levels of IL-6, IL-2R, IL-10, TNF-α, IL-1β, IL-4, IL-8 and IL-17 were significantly elevated in the severe or death cases and probably play crucial roles in the progression of COVID-19." (PMID 35237162, 2022). "Regardless of the existence of a direct interaction of miR-144 with IL-10 and EGF, we found that combined scores increased discriminatory power of disease severity and the prediction of mortality in COVID-19 patients, providing a robust stratification tool." (PMID 36414650, 2022). "Our findings also align with the results of a study conducted on 41 COVID-19 confirmed cases in China, which found that IL-6, IL-7, TNF, and IL-10 were upregulated in the plasma of the study subjects." (PMID 36239108, 2022). "The increment of IL-10 and Gal-1 as well as strong positive correlation between them in stage III of COVID-19 implicate on Gal-1 and IL-10 dependent immunomodulation." (PMID 35075140, 2022). "In contrast, we found that plasma IL-6, IFN-α, IFN-γ, IL-1β, TNF-α, IL-10, IP-10, MIG and MCP-1 levels were significantly higher in severe COVID-19 compared to healthy controls." (PMID 35422799, 2022).
COVID-19 (continued). "In critically ill COVID-19 patients predominantly admitted for ECMO evaluation, IL-10 supported the discrimination of bacterial/fungal secondary infections from inflammation caused by COVID-19 and/or ECMO." (PMID 36275812, 2022). "IL-6, IL-8, IL-10, and TNF-α were increased in severe cases of COVID-19 while IFN-α, IL-1β, IL-4, and IL-15 were enriched in mild cases." (PMID 35685940, 2022). "In fact, by shifting RAAS toward ANGII/AT1R, the level of inflammatory cytokines such as IL4, IL10 and IL6 are increased, which in turn activates T-cells in peripheral blood of COVID-19 patients." (PMID 36128671, 2022). "MMP-7, TGF-β, CCL2, CCL-3, CXCL-10, G-CSF, IFN gamma, IL-10, IL-2, IL-4, IL-6, IL-7, TNF-α, IL-6, and IGF-1 were studied for their correlation to lung involvement in COVID-19 patients." (PMID 36286038, 2022). "High levels of pro-inflammatory markers (IL-6, IL-8, IL-10, and TNF-α) were detected in the cerebrospinal fluid (CSF) collected from COVID-19 patients exhibiting neurological symptoms and/or meningoencephalitis." (PMID 35625737, 2022). "As an indication of disease severity, we measured the mRNA expression levels of IFN-stimulated genes (IFIT1, IFIT3, ISG15, and MX2), pro-inflammatory cytokines (IL6, IL10), and chemokines (CXCL10, CCL2) that are correlated with COVID-19 exacerbation." (PMID 35562337, 2022). "In COVID-19 patients, high levels of TNF-α, IL-1β, IL-4, IL-6, IL-10, IP-10, MCP-1, and MIP-1A have been detected, and particularly, high IL-6 concentrations are positively correlated with the severity of the disease." (PMID 35744777, 2022). "Initial studies in Wuhan, China showed elevated IL-1β, IL-7, IL-8, IL-9, IL-10, FGF, G-CSF, GM-CSF, IFN-γ, IP-10, MCP-1α and 1β, MIP-1, PDGF, TNF-α, and VEGF concentrations in COVID-19 compared to uninfected individuals." (PMID 35401519, 2022). "In Case 3, the spontaneous production of cytokines (IL-1ß, IL-10, IL-12, and TGF-ß) prior to COVID-19 exposure was higher following a marked exacerbation of his neuropsychiatric symptoms (time point 2)." (PMID 36579544, 2022). "Plasma levels of IL-1RA, IL-10, IL-15, and G-CSF and of the chemokines CCL3, CCL4, CXCL8, and CXCL10 were significantly increased in patients with COVID-19 compared with those of healthy controls." (PMID 34793331, 2022). "Higher levels of interleukin IL-6 and IL-10, and lower levels of CD4+T and CD8+T are also observed in patients with COVID-19 and these correlate with the severity of disease." (PMID 33643932, 2021). "The therapeutic efficacy of SHXP against COVID-19 is likely mediated via the regulation of 4 targets, namely, IL6, IL10, VEGFA, and TNF." (PMID 34941025, 2021). "Vice versa, IL10-signaling (which inhibits the IFN-response), chemokine receptor binding and ATF4-mediated ER stress response were increased in critical COVID-19." (PMID 33473155, 2021). "Inflammatory parameters (IL-6, IL-10, TNF-alpha, IFN-gamma, MCP-1) were increased in COVID-19 patients with severe illness." (PMID 35136584, 2021). "So far, it is the first clinical study investigating the role of circulating inflammatory and nociceptive molecules such as HMGB1, NLRP3 inflammasome, IL-6, IL-10, angiotensin II, and ACE2 in COVID-19 headache." (PMID 34384355, 2021). "IL-6, CXCL10, CXCL9, CCL2, IL1-Ra, IL-10, G-CSF and TNF-α were the cytokines with the highest contribution to dimension 2 in the PCA and were significantly increased in acute COVID-19 patients in comparison to HC." (PMID 34572439, 2021). "A recent study demonstrated that COVID-19 severe patients had a low level of counts of T cells and a high level of IL-2, IL-6, IFN-γ, and IL-10 compared with the mild patients, similar to the results in SARS and MERS." (PMID 33833618, 2021). "The increase in blood concentrations of different cytokines such as interleukins and chemokines such as IL-6, IL-8, IL-10, TNF-α, IL-1β, IL-2, IP-10, MCP-1, CCL3, CCL4, and CCL5 has been described for COVID-19 patients." (PMID 34262570, 2021).
COVID-19 (continued). "Compared to younger patients under 60 years old with COVID-19, levels of CRP, PCT, and IL-10 were all significantly increased in elderly patients." (PMID 33735325, 2021). "Corroborating this suggestion, a positive correlation was found between IL-10 and IFN-α and IFN-γ in both mild COVID-19 subgroups." (PMID 33717074, 2021). "Importantly, because T2D is a risk factor for increased COVID-19 disease severity and mortality (which is markedly lower with well-controlled blood glucose levels), IL-10 resistance may provide a mechanistic link between hyperglycemia/T2D and adverse COVID-19 outcomes." (PMID 34234779, 2021). "Meanwhile, expression of IRF4 is associated with the secretion of IL-4 and IL-10 which are anti-inflammatory cytokines that may be important to reduce the damage of the cytokine storm in moderate patients and not develop in severe COVID-19 symptoms." (PMID 34603282, 2021). "Dysregulated immune response and cytokine storm, with elevated levels of IL-6, IL-10, and TNF-α, and lymphopenia, correlated with worse outcomes in COVID-19 patients." (PMID 34439920, 2021). "Evaluation of cytokines at week 2 revealed that the levels of IL-4, IL-6, IL-10, and IFN-γ were higher, while the levels of IL-2 were lower in COVID-19 patients than that in HC." (PMID 33390771, 2021). "It was reported significantly increased plasma levels of pro-inflammatory cytokines, including IL-1β, IL-6, IL-7, IL-8, IL-9, IL-10, interferon (IFN)-γ, and TNF-α in patients with COVID-19 than in healthy adults, but similar levels of IL-5, IL12p70, and IL-15." (PMID 34595175, 2021). "Our multivariate model showed that COVID-19 was related to increased expression levels of TNF-α, IL-1β, IL-6, IL-8, IL-12B, and IL-10 (P < 0.05), and that leprosy simultaneously enhanced the levels of IL-6 (P = 0.046) and IL-12B (P = 0.020)." (PMID 33819170, 2021). "A variety of inflammatory or anti-inflammatory cytokines, such as interleukin (IL)-1β, IL-6, IL-8, IL-10, and interferon (IFN)-γ, were elevated in severe COVID-19 patients." (PMID 34367188, 2021). "COVID-19 patients are also reported to show CD4+ lymphopenia; CD8+ lymphopenia; and higher levels of cytokines such as interleukin (IL)-6, IL-10, and tumor necrosis factor alpha (TNF-α)." (PMID 34360684, 2021). "Finally, several lines of evidence suggest that the early and dramatic IL-10 elevation upon SARS-CoV-2 infection might play a detrimental pathological role in critically COVID-19 patients and IL-10 has also been proposed as a potential target for reducing COVID-19 mortality." (PMID 33673459, 2021). "Our results showed that with the severity of COVID-19 worsens, the count of WBC, NEUT, IL-6, and IL-10 increased significantly, while LYM levels decreased." (PMID 33557779, 2021). "GCSF, IL-1RA, IL-6, IL-8, IL-10, IL-12 (p40), MCP-1, M-CSF, and TNF-α were correlated with SOFA scores in COVID-19 patients and controls, with increased cytokine expression positively correlating with higher SOFA scores." (PMID 34131192, 2021). "Studies have shown that the levels of various cytokines such as IL-2R, IL-6, IL-10, IL-2, IL-7, GCSF and TNF-α are significantly higher in patients with severe COVID-19 compared with patients who have a mild disease." (PMID 34490065, 2021). "Increased expression of the cytokines IL-6, IL-10, and TNF-α is closely related with severe COVID-19." (PMID 34484133, 2021). "Compared with patients in severe COVID-19, those who in critical COVID-19 had significantly higher levels of tumor necrosis factor-α (TNF-α), interleukin-6 (IL-6), IL-8, and IL-10." (PMID 34725309, 2021). "Like IL-1Ra, IL-10 likely exerts an inhibitory effect on hyperinflammation, evidenced by elevated IL-10 levels in active AOSD and severe COVID-19." (PMID 34367188, 2021). "As for wave 1, significant differences and increasing trends of IL-1β, IL-1ra, IL-2, IL-6, IL-8, IL-10, GM-CSF, IFN-γ, IP-10, were observed in the three groups (Controls ≤ Mild COVID-19 ≤ Severe COVID-19)." (PMID 34675240, 2021).
COVID-19 (continued). "Therefore, IL-6 and IL-10 can be used as predictors for rapid prognosis of COVID-19 patients with higher risk of disease deterioration, and the neutrophil-to-lymphocyte ratio and neutrophil-to-CD8+ T cell ratio have been identified as powerful predictors of severe COVID-19." (PMID 34818337, 2021). "Investigators discovered a negative correlation between T cell numbers and the concentration of cytokines including interleukin-6 (IL-6), IL-10, interferon-γ (IFN-γ), and tumor necrosis factor-α (TNF-α) in COVID-19 patients." (PMID 34766001, 2021). "Three BIMs: MAP2, NSE and S100B, two EIMs: sICAM1 and sVCAM1 and seven CCs: GRO IL10, sCD40L, IP10, IL1Ra, MCP1 and TNFα were significantly (p < 0.05) elevated in the COVID-19 cohort compared to controls." (PMID 34838058, 2021). "We reported that patients affected by COVID-19 showed an increase of plasma level of cytokines with different properties, such as CCL4, IL-10, and PD-L139." (PMID 34326336, 2021). "In a recent study, decreased number of Tregs with a decreased expression of FoxP3 mRNA and immunosuppressive cytokines (IL-10 and TGFβ) was reported in PBMC derived from the COVID-19 patients treated in ICU." (PMID 34895167, 2021). "Meanwhile, COVID-19 displayed an immune profile distinguished by increased Th1 (IL-12, IFN-γ) and Th2 (IL-4, IL-5, IL-10, IL-13) cytokine levels, along with IL-1β, IL-6, CCL11, VEGF, TWEAK, TSLP, MMP-1, and MMP-3." (PMID 33995342, 2021). "Studies have shown a strong correlation between the severity of COVID-19 and concentrations of different cytokines, such as IL2, IL7, IL10, GCSF, MCP1, and TNF-alpha." (PMID 33796097, 2021). "Compared to those alive, all the patients who died from COVID-19 had increased levels of TNF-α, IL-2R, IL-6, IL-8, and IL-10 tested on admission." (PMID 33735106, 2021). "Although appropriate levels of proinflammatory cytokines are required to activate immune cells involved in viral control, extremely high levels of IL-1β, IL-10, G-CSF, GM-CSF, IFN-γ and TNF-α were detected in COVID-19 patients." (PMID 34439920, 2021). "In contrast, the levels of IL-10 and PDGF-BB were significantly lowered amongst COVID-19 recovered patients as compared to healthy individuals." (PMID 34122129, 2021). "The areas under ROC curves (AUROCs) were 0.868 for NLR, 0.811 for IL-6, 0.802 for IL-2R, 0.763 for IL-8, 0.731 for IL-10 and 0.699 for TNF-α when performing prediction of severe or critical COVID-19 cases." (PMID 34282057, 2021). "These migratory DCs express IL10 in health, but TNF and the common IL-12 and IL-23 subunit IL12B in COVID-19, suggesting altered capacity for T cell polarization." (PMID 33879890, 2021). "Several investigators reported a negative correlation between T cell numbers and the concentration of cytokines including interleukin-6 (IL-6), IL-10, interferon-γ (IFN-γ), and tumor necrosis factor-α (TNF-α) in COVID-19 patients." (PMID 34522871, 2021). "Assessment of infection-related biomarkers (CRP, ESR) and cytokine profile (IL-2R, IL-6, IL-8, IL-10, IL-1β, TNF-α, procalcitonin) on admission showed a proinflammatory state in hemodialysis patients with COVID-19." (PMID 33967613, 2021). "Seven core targets of vitamin A against COVID-19, including CAT, EGFR, ICAM1, IL10, MAPK1, MAPK14, and PRKCB, have been detected." (PMID 34335237, 2021). "A recent study has linked the IL-6-mediated signaling axis with MCP-1, IL-8, and IL-10 to the elevation of PAI-1, recently shown to be elevated in COVID-19 patients." (PMID 34452463, 2021). "Search for targets of these miRNAs, combined with plasma protein measurements, identified a differential cytokine signature between COVID-19 and CAP that included EGFR, CXCL12 and IL-10." (PMID 35087533, 2021). "A previous study displayed that serum levels of IL-6, IL-10, and TNF-α increase with disease severity in patients with COVID-19." (PMID 35155477, 2021).
COVID-19 (continued). "In severe COVID-19 patients, serum levels of proinflammatory cytokines including IL-2, IL6, IL-7, IL-10, G-CSF, IP-10, MCP-1, MIP-1α and TNFα are highly elevated." (PMID 33643932, 2021). "Previous studies have reported abnormal levels of IL-2, IL-6, IL-7, IL-10, CRP, and tumor necrosis factor-α in COVID-19 patients." (PMID 34242179, 2021). "Kaplan-Meier survival curves showed that higher IL-2R, IL-6, IL-8, IL-10, and TNF-α levels were significantly correlated with reduced survival time in COVID-19 (all P < 0.001)." (PMID 33542929, 2021). "It remains to be defined why COVID-19 patients had severe and critical clinical characteristics independent of circulating levels of inflammatory cytokines (IFN-γ, TNF-α, IL-2, IL-4 and IL-10)." (PMID 34123873, 2021). "Regarding the mild B COVID-19 subgroup, it was observed significant positive correlations between IFN-α and IFN-γ, and also between these interferons and IL-6 and IL-10." (PMID 33717074, 2021). "COVID-19-related CRS patients exhibited increased plasma levels of IL-2, IL-7, IL-10, G-SCF, MCP-1, MIP-1α, and TNF-α." (PMID 34884813, 2021). "Since a cytokine storm is one of the complications of COVID-19, some of the MAbs are also targeted against proinflammatory mediators, such as TNF-α, IL-4, and IL-10." (PMID 34769383, 2021). "In the clinical treatment of patients with COVID-19, Xuebijing Injection mainly inhibited IL6, TNF-α, MCP1, mip2, and IL10 to inhibit inflammatory response." (PMID 34335247, 2021). "Lymphocyte count was negatively associated with IFNγ, IL-2, TNFα, IL-1α, IFNβ, IL-6, IL-17A, IL-10, CXCL-10 and VEGF in children with PIMS-TS and COVID-19." (PMID 33813138, 2021). "In COVID-19 headache patients who are unresponsive to paracetamol, HMGB1 level was significantly elevated (989.3 ± 263.5 vs 514.7 ± 248.9, p < 0.001) whereas IL-10 level (16.1 ± 11.9 vs 19.4 ± 5.6 p = 0.017) was decreased." (PMID 34384355, 2021). "Individuals with severe COVID-19 have markedly reduced numbers of CD4+ and CD8+ T cells, and lymphocyte counts negatively correlate with levels of serum IL-6, IL-10, and TNF-α." (PMID 34440767, 2021). "Thus, as IL-10 may be responsible for this depression, either by inducing T cell reduction or exhaustion, it is possible that IL-10 blockade may serve as a potential therapeutic approach for COVID-19." (PMID 34251989, 2021). "It has been reported that monocytes involved in COVID-19, similar to monocytes involved in HCV, overexpress PD-L1 and IL-10." (PMID 34163490, 2021). "A set of cytokines were upregulated in SputnikV immunized individuals (IL-1α, IL-3, IL-10, IL-12p70, CCL7, IFN-α2, bFGF, LIF and TRAIL), where nine of them were similar to that in convalescent COVID-19." (PMID 34681885, 2021). "Accordingly, the results of the present study demonstrated that patients with severe COVID-19 had higher levels of several inflammatory biomarkers (e.g., NLR, CRP, procalcitonin, PCT, IL-6, and IL-10 levels)." (PMID 33763027, 2021). "Our present results identified obvious elevations of various cytokines in patients with severe COVID-19, including IL-1α, IL-1β, IFN-γ, TNF-α, IL-2, IL-4, IL-6, IL-10, and IL-17A." (PMID 34113636, 2021). "Seventy-one studies were included involving 8647 COVID-19 patients, White blood cell (WBC), neutrophil (NEUT), IL-6, and IL-10 counts increased significantly with worsening of the COVID-19, while lymphocyte (LYM) counts decreased." (PMID 33557779, 2021). "In our study, we found that the core pathogenesis target of COVID-19 was TNF, while the secondary pathogenesis targets included IL6, IL10, and IL2 cytokines." (PMID 34731090, 2021). "In particular, Gal-9, IL-6, IP-10, IL-10, and TNF-α were substantially higher in COVID-19 patients versus HCs." (PMID 33947753, 2021).